S1PR1 (sphingosine-1-phosphate receptor 1)
Diseases named in the same sentence as S1PR1 in open-access papers (continued):
Sharing a sentence is not in itself a finding about the gene and the disease.
heart injuries (1 paper, 2025). "Collectively, these results confirm that the CM-expressing S1PR1 plays a crucial role in regulating cardiomyocyte proliferation and apoptosis during cardiac regeneration following heart injuries." (PMID 39816679, 2025). "Our in vivo experiments, involving both CM-specific S1pr1 loss-of-function and gain-of-function, strongly support the crucial role of S1PR1 in regulating cardiac regeneration and promoting cardiac repair and functions after heart injuries." (PMID 39816679, 2025). "Our study revealed that tamoxifen-inducible CM-specific S1pr1 deletion significantly reduced cardiomyocyte proliferation and hindered heart regeneration in neonatal mice after heart injuries." (PMID 39816679, 2025).
helminth infection (1 paper, 2022). "Intriguingly, helminth infection changed the global distribution and activation of murine ILC2s through the induction of S1PR1-dependent egress of gut ILC2s and accumulation in the lungs, suggesting a coordinated response to protect distal body sites targeted by helminth infection." (PMID 35359972, 2022).
impetigo (1 paper, 2024). A pyoderma consisting of three forms of skin lesions having either a thick, adherent, recurrent, dirty yellow crust with an erythematous margin (common or superficial impetigo) or lessions which are superficial, thin-walled, and bullous as found in bullous impetigo. "Higher expression levels of S1PR1 and S1PR2 observed in the skin of impetigo patients and changes in the distribution patterns of these receptors were also aligned with these findings." (PMID 38862781, 2024).
invasive breast carcinoma (1 paper, 2020). A carcinoma that infiltrates the breast parenchyma. "IL-22R1, S1PR1, and MMP-9 were found to be predominantly expressed in metastatic breast carcinoma specimens but only weakly detected in normal tissues and invasive breast carcinoma (left)." (PMID 31935914, 2020).
liver cancer (1 paper, 2022). An epithelial or non-epithelial malignant neoplasm that arises from the liver. "Further experiments using a serial tissue microarray confirmed that S1PR1 was selectively expressed in CD31+ cells and was expressed at low levels in hepPar1 (a liver/liver cancer cell marker)-positive cells." (PMID 36068200, 2022).
liver failure (1 paper, 2025). A liver disease characterized by the liver losing or has lost all of its function. "Indeed, in LPS/D-galactosamine (D-Gal)-induced liver failure, S1P levels were elevated, whilst the expression of SphK1, S1PR1, and S1PR3 was upregulated in the liver, and the levels of serum markers of liver failure, AST and ALT, and the serum cytokines TNF-α, IL-1, and IL-6 were increased." (PMID 39935473, 2025).
lymph node metastasis (1 paper, 2019). "We found that high expression of S1PR1 significantly correlated with high histological grade, lymph node metastasis and advanced clinical stage." (PMID 31438989, 2019).
lymphedema (1 paper, 2026). Excess fluid collection in tissues, causing swelling. "In contrast, reduced S1pr1 levels have been reported in inflamed dermal lymphatics in the setting of lymphedema." (PMID 41381806, 2026).
meningococcal meningitis (1 paper, 2023). "Conversely, pharmacological activation of S1PR1 and 3 had an even higher protective effect against bacterial invasion, indicating that the S1P/S1PR axis is actively manipulated by N. meningitidis and thus highlighting potential drug targets to prevent meningococcal meningitis." (PMID 38033162, 2023).
metastasis (1 paper, 2019). The spread or migration of cancer cells from one part of the body (where they first appeared) to another. "Aberrant co-expressed of S1PR1 and p-STAT3 was not correlated with any clinicopathological factors, except for a positive correlation with metachronous liver metastasis (P = 0.022)." (PMID 31534132, 2019).
ocular infection (1 paper, 2024). "Because γδ T cells can be tissue resident, we needed to determine whether corneal γδ T17 cells were S1PR1 dependent during HSV-1 ocular infection." (PMID 39504049, 2024).
Pain (1 paper, 2022). An unpleasant sensory and emotional experience associated with actual or potential tissue damage, or described in terms of such damage. "Additionally, activation of S1PR1 is involved in opioid-induced-hyperalgesia and fingolimod, by antagonistic effects on S1PR1, attenuates the development of morphine-induced persistent neuropathic pain in rats." (PMID 35250559, 2022).
renal fibrosis (1 paper, 2013). A final common manifestation of a wide variety of chronic kidney diseases characterized by glomerulosclerosis and tubulointerstitial fibrosis. "Renal fibrosis has been shown to occur through inflammatory pathways involving S1PR1." (PMID 24744854, 2013).
respiratory infection (1 paper, 2020). "Prioritization of candidate modifier genes within the QTL led us to select the S1pr1 gene for functional validation of its relevance for respiratory infection." (PMID 32127447, 2020).
severe acute respiratory syndrome (1 paper, 2021). A viral respiratory infection caused by the SARS coronavirus. "It is also believed that host-directive therapy using modulators of S1PR1 and other S1PRs may be an effective treatment against severe infectious diseases, such as severe acute respiratory syndrome (SARS) and COVID-19." (PMID 34934406, 2021).
thrombosis (1 paper, 2022). "This two‐photon imaging study provides the novel evidence that selective S1PR1 modulation enhances the thrombolytic effect of low-dose tPA in cerebral arterioles after thrombosis." (PMID 35720286, 2022).
urothelial carcinoma (1 paper, 2021). A malignant neoplasm derived from the transitional epithelium of the urinary tract (urinary bladder, ureter, urethra, or renal pelvis). "In this study, we collected six databases of urothelial carcinoma with accompanying survival status and follow-up time for the association between S1PR1 expression and patient prognosis." (PMID 34503284, 2021).
tumor (215 papers, 2006 to 2026). "To elucidate the disparate expression of S1PR1 between tumor and normal tissues in LUAD patients and its association with clinical outcomes, we conducted a comprehensive analysis of the RNA expression matrix." (PMID 39551792, 2024). "S1PR1 on tumor-associated macrophages promotes lymphangiogenesis and tumor metastasis in breast cancer patients through the NLRP3/IL-1 pathway." (PMID 37803421, 2023). "Meanwhile, it has also been reported that GBM can cause the loss of S1PR1 on the surface of T cells, thus confining a large number of T cells to the bone marrow and preventing them from exerting anti-tumor effects." (PMID 36483052, 2022). "A similar analysis also revealed that S1PR1 expression was associated with genes that comprised the tumor vasculature signature." (PMID 36361536, 2022). "Interrupting a direct impact of S1P on endothelial cells appears unlikely, since S1P was recently shown to stabilize tumor-associated blood vessels via endothelial S1PR1 (as well as S1PR2/3) signaling." (PMID 35163211, 2022). "Tumor-associated blood vessel stabilization by endothelial S1PR1 appeared to shift the tumor immune profile from myeloid towards lymphoid cells, although it is not clear if that relies on differences in diapedesis across leaky versus stabilized blood vessels." (PMID 35163211, 2022). "To further confirm the underlying mechanism by which BAF312 inhibits tumor growth and antivascular formation, we conducted immunohistochemical analysis, and the results indicated that S1PR1, P-STAT3, and VEGFA were downregulated." (PMID 34059068, 2021). "We found that S1PR1 was significantly associated with vasculogenesis, the purinergic receptor signaling pathway, and metabolism of nucleic acids in tumor conditions." (PMID 32799825, 2020). "S1P was shown to selectively promote the expression of NLRP3 among inflammasome components downstream of S1PR1 in tumor-associated macrophages (TAM), as well as LPS-stimulated mouse BMDM and human primary monocyte-derived macrophages." (PMID 31379883, 2019). "For example, a previous study exhibited that the expression of S1PR1 mRNA was associated with tumor staging in esophageal carcinoma." (PMID 31438989, 2019). "Improved prognosis in patients with GBMs has been associated with the high expression of S1PR1, suggesting its function as a tumor suppressor." (PMID 29805753, 2018). "S1PR1 in tumor cells was previously shown to be linked to STAT3 activation, which contributed to stimulated IL-6 production." (PMID 28771545, 2017). "Cell sorting and transcriptome analysis of TAMs from both tumor entities revealed reduced expression of the inflammasome component Nlrp3 in S1PR1-deficient TAMs, which correlated with decreased IL-1β levels in tumor tissue." (PMID 28804221, 2017). "FTY720 directly or indirectly acts on S1PR1, which may cause G protein-coupled receptor dysfunction of tumor cells, affect cell proliferation and migration, and promote cell apoptosis." (PMID 41154714, 2025). "In many cases, the inflammatory TME contributes to metastasis by recruiting blood and lymph vessels, such as the S1PR1 on tumor-associated macrophages (TAMs), which triggers lymphangiogenesis, tumor angiogenesis, and metastatic spread via NLRP3/IL-1β in pulmonary cancer." (PMID 35892884, 2022). "Nevertheless, whether S1PR1 expression in tumor cell may affect the generation of tumor-associated endothelial cells requires further investigation." (PMID 34503284, 2021). "The association between high S1PR1 expression and poor prognosis may be due to tumor invasion of adjacent normal tissues, where highly expressed S1PR1 may affect prognostic interpretation." (PMID 34503284, 2021). "In addition, the association of S1PR1 with tumor purity and immune cell infiltration was comprehensively analyzed." (PMID 34503284, 2021). "S1PR1 expression is thought to be associated with poor prognosis, but it is unknown whether it is associated with tumor metastasis." (PMID 34503284, 2021).
tumor (continued). "Furthermore, the loss of S1PR1 in T-cell dysfunction for anti-tumor activities is under investigation (NCT04657146)." (PMID 35201458, 2021). "Samples collected from high-grade tumor cells are more likely to be adulterated with normal tissue, which may explain the association of high S1PR1 expression with poor prognosis observed in some databases." (PMID 34503284, 2021). "However, a brain‐specific mechanism by which tumours escape immunosurveillance though the loss of S1PR1 on T cells was discovered." (PMID 32155312, 2020). "However, previous results are contradictory, possibly because the dual angiogenesis patterns prevent S1PR1-related signals from blocking EDV but cause tumor cells to produce self-sufficient blood supply patterns (VM)." (PMID 30814488, 2019). "For instance, S1PR1-deficient mice die in utero from massive hemorrhage due to immature vessel development, and neutralization of extracellular S1P with anti-S1P antibody demonstrates a significant inhibition of angiogenesis, tumor growth, and metastasis." (PMID 29147072, 2017). "S1PR1 was found mutated in four tumor samples derived from two patients." (PMID 27224912, 2016). "Given that S1PR1 and pSTAT3 closely co-operate during inflammatory and immunologic processes and neoplasms, the S1PR1/pSTAT3 risk category was developed to help stratify the risk of rituximab-treated DLBCL patients using immunohistochemistry for S1PR1 and pSTAT3." (PMID 25472725, 2014). "Besides T cells, S1PR1 was also involved in STAT3 activation in tumor-associated myeloid cells." (PMID 35163211, 2022). "This study was aimed to investigate the factors affecting the localization of S1PR1 on the surface of lymphatic endothelial cells and its role in tumor lymphangiogenesis." (PMID 39991586, 2025). "CERS6 and SPTLC2 were classified into a high-risk group with higher hazard ratios (HR > 1) and higher expression in tumor tissues, but S1PR1 exhibited a protective effect (HR < 1) and lower expression in malignant tissues." (PMID 40057751, 2025). "Many effects of S1P in the tumor microenvironment are mediated by its binding to its five G protein-coupled receptors, primarily S1PR1-3, thereby inducing migration and metastasis in various cell types." (PMID 40069781, 2025). "In HSCs, S1pr1-3 was upregulated in the pre-tumor group, but only S1p3 was further upregulated in the HCC group." (PMID 40057751, 2025). "Our findings unveiled a new role of extracellular matrix in tumor microenvironment in regulating S1PR1 redistribution." (PMID 39991586, 2025). "Here we attempt to investigate hyaluronan fragments abundant in tumor microenvironment (TME) on S1PR1 in new lymphatic vessel formation." (PMID 39991586, 2025). "S1P promotes the secretion of vascular endothelial growth factor (VEGF) through S1PR1/S1PR3, playing a central role in tumor angiogenesis while circulating S1P relies on S1PR1 to maintain endothelial barrier integrity and inhibit inflammatory vascular leakage." (PMID 41234914, 2025). "S1PR1 has been reported to be upregulated by ApoM overexpression, which promotes proliferation and invasion in vitro as well as tumor growth in vivo in the A549 cell line." (PMID 39551792, 2024). "More recently, we have shown that the S1PR1 inhibitor siponimod, when used as a single agent, can reduce angiogenesis and tumor growth in an animal model of angiogenic DLBCL." (PMID 38339325, 2024). "S1P/S1PR1 signaling plays an important role in the growth, infiltration, metastasis, angiogenesis, and autophagy of various types of tumor cells by regulating the STAT, ERK, Akt and Rac pathways." (PMID 38446289, 2024). "In contrast to distal bone marrow, the CB niche proximal to the tumor showed increased frequencies of tumor-reactive CD8+ effector types expressing the lymphoid egress marker S1PR1." (PMID 39085419, 2024). "Although we cannot rule out a contribution from S1PR5, we conclude that the in vitro migration of monocytes and macrophages to tumor-derived S1P is S1PR1-dependent." (PMID 38339325, 2024).
tumor (continued). "Their effector types are characterized by an enduring tumor response, and, compared to cells from the dBM, by an increased expression of the lymphoid egress marker S1PR1." (PMID 39085419, 2024). "Enhanced S1PR1 signaling has also been shown to consistently activate NF-κB and STAT3, the major transcription factors associated with tumor growth and metastasis." (PMID 38523645, 2024). "To confirm that lymphocyte exit from the tumor and into the draining lymphatics is an active process, we examined the role of exit signals via S1P on T cells expressing S1PR1." (PMID 38789721, 2024). "The role of S1PR1 in enhancing the malignant potential of tumor cells is well-documented in various malignancies." (PMID 39551792, 2024). "The upregulation of S1PR1 can activate STAT3, which binds to the promoter of S1PR1 to regulate its transcription, forming a positive feedback loop and accelerating tumor growth and metastasis." (PMID 38163890, 2024). "Nevertheless, S1PR1 on ECs is necessary for tumor vascular normalization to allow improved blood circulation and enhance antitumor therapy in mouse models." (PMID 37142226, 2023). "As S1P signaling through its receptors on macrophages seems to be a potent driving factor for recruiting macrophages in GB, S1PR1/2 expression in microglial cells and S1P secretion by tumor cells likely contribute to tumor aggressiveness." (PMID 36672428, 2023). "It is worth mentioning that S1PR1 plays an indispensable role in maintaining persistent activation of STAT3 by regulating tumor cells and tumor-infiltrating myeloid cells in primary tumors." (PMID 36714534, 2023). "YAP can further regulate the expression of S1PR1, and this positive feedback regulation leads to tumor cell senescence inhibition and exacerbated tumor cell proliferation." (PMID 37828220, 2023). "FTY720 acts to block S1PR1 and thus prevent the egress of immune cells from lymph nodes into the tumor site." (PMID 37914685, 2023). "As a bioactive lipid mediator, S1P can mediate signal transduction by combining with the cell surface receptor S1PR1, which has been proven to enhance the proliferation, survival, and metastasis of tumor cells." (PMID 36714534, 2023). "The S1PR1 signaling pathway mediates the production of various oncogenic regulators involved in tumor angiogenesis and immune cell migration." (PMID 37828220, 2023). "Inhibition of S1PR1 expressed in tumor vessels effectively reduces angiogenesis and delays tumor growth in vivo." (PMID 37220855, 2023). "At the end of the experiment, the tumor volume in S1PR1 knockout mice was smaller than that in wild-type mice." (PMID 37828220, 2023). "Western blot results showed that S1PR1, cyclin B1, PDK1, and lamin B1 protein levels were significantly decreased, whereas P21, P62, histone H3, IGFBP7, and PAI-1 protein levels were significantly increased in S1PR1 knockout tumor tissue." (PMID 37828220, 2023). "It was previously found that S1PR1 was expressed abundantly in ECs, had angiogenic effects in tumours and was a regulator or the receptor of S1P." (PMID 36068200, 2022). "In this animal model, a specific S1PR1 agonist, SEW-2871, which activates S1PR1, blocked cytotoxic T lymphocyte anti-tumour function." (PMID 35158806, 2022). "For another T cell subset, namely Tregs, S1PR1 expression is also an important cue for migration to the tumor site." (PMID 35163211, 2022). "Its importance in regulating T cell trafficking via the circulation would lead to the expectation of reduced anti-tumor immunity once S1PR1 is targeted." (PMID 35163211, 2022). "This has been further confirmed by experiments showing that prevention of S1PR1 activation inhibits tumour growth, metastasis and persistent STAT3 activation." (PMID 35563301, 2022). "The expression of NOG and S1PR1 genes was also increased in CFP1-deleted tumor tissue cells, while the expression of RASSF9 and BST2 was decreased significantly." (PMID 35864225, 2022).